SMC1A (structural maintenance of chromosomes 1A)
Diseases named in the same sentence as SMC1A in open-access papers (continued):
Sharing a sentence is not in itself a finding about the gene and the disease.
cancer (44 papers, 2012 to 2025). A tumor composed of atypical neoplastic, often pleomorphic cells that invade other tissues. "Considering the role of SMC1A in DNA repair and genome stability maintenance, SMC1A variants have been only recently identified in human cancers, even if the role of these variants in oncogenesis is yet to be fully understood." (PMID 41153413, 2025). "Although rare, somatic mutations in SMC1A have been identified in several cancers, implying a potential role in oncogenesis through impaired chromosome segregation and genome instability." (PMID 41153413, 2025). "Recently, there is evidence that SMC1A is implicated in the pathogenesis of rare diseases and cancers." (PMID 37096492, 2023). "Here, we demonstrate that a cancer-associated mutation to the hinge domain of SMC1A results in striking changes to gene expression and genome organization." (PMID 33760811, 2021). "Since a large number of cancers, and especially blood cancers, exhibit loss of cellular identity, knocking the SMC1A-R586W mutation into mESCs allows for investigation of potential aberrant cellular identity and the molecular mechanisms that underlie it." (PMID 33760811, 2021). "We use publicly available cancer exome sequencing data to identify a hotspot mutation at amino acid residue 586 in the hinge of SMC1A." (PMID 33760811, 2021). "While cancer cells are generally thought to grow and divide rapidly, the SMC1A-R586W mutation causes decreased proliferation of mESCs." (PMID 33760811, 2021). "It is worth noting that 5 out of 13 carcinoma samples carried from two to four SMC1A mutations whereas two subjects (9 and 12) carried the same mutation (c.A950G) at the carcinoma stage." (PMID 30823889, 2019). "We found extra-copies of SMC1A gene in carcinomas and subsequent sequencing revealed the presence of mutations." (PMID 30823889, 2019). "Finally, we examined the effect of SMC1A knockdown on anchorage-independent growth, a hallmark of cancer cells associated with their tumorigenic potential." (PMID 38365745, 2024). "Furthermore, the finding that neutral mutations were identified only in carcinomas suggests that the mutation rate of SMC1A is higher in carcinoma than in the early stage of cancer development." (PMID 30823889, 2019). "Interestingly, altered RAD21 or SMC1A expression was also reported as associated with distinct cancer phenotypes, although the complete mechanism of cohesin biology remains to be determined." (PMID 25963978, 2015). "In addition to CRC, SMC1A mutations are associated with other human cancers." (PMID 35287703, 2022). "In cancer, aberrant SMC1A expression or function can contribute to tumor proliferation, cell-cycle dysregulation, and apoptotic resistance, making cohesin a potential therapeutic target." (PMID 41153413, 2025). "Correlations between p-SMC1A expression, subcellular localization, and clinicopathological characteristics such as cancer stage, histological grade, and subtypes were examined." (PMID 39851557, 2025). "The volume of tumors was significantly decreased upon silencing of the SMC1A gene while its upregulation had a positive impact on cancer progression." (PMID 38365745, 2024). "The present findings show that SMC1A knockdown alone or in combination with bevacizumab impairs cancer growth, translating into a consistent improvement in animals’ overall survival." (PMID 38365745, 2024). "It is plausible that SMC1A has a role in the chemoresistance of GC cells given the growing body of research demonstrating that cancer cells undergo EMT and contribute to this resistance, However, investigations are required to validate this idea." (PMID 37537540, 2023). "In this study, SMC1A has the potential to serve as a bidirectional target switch, regulating both the immune microenvironment and cancer stem cells simultaneously." (PMID 37096492, 2023).
cancer (continued). "Our findings demonstrated that SMC1A is an oncogene that is highly expressed in numerous clinical cancer tissues compared with normal tissues, including COAD." (PMID 37096492, 2023). "To examine the involvement of SMC1A in clinical cancer patients, we first investigated the mRNA levels of SMC1A in all tumor samples and normal tissues in the TCGA and GTEx databases." (PMID 37096492, 2023). "Among cancer-related genes, CARD11(18%) and IRS1(18%) were the most common somatic mutated genes, followed by PSMD11, RELN, RRAS2, SMC1A, SYNE1 and ZFHX3, and the mutation rates of the latter six genes were all 14%." (PMID 36457486, 2022). "The core complex subunits SMC1A, SMC3, STAG1/2, and RAD21 as well as its modulators, have been found to be recurrently mutated in human cancers." (PMID 35287703, 2022). "Next, we focused on SMC1A gene because its mutations have been identified in CRC and in other cancers and cause CIN and chromosome aneuploidy in vitro." (PMID 30823889, 2019). "Robust SMC1A expression was observed in most of the carcinomas, 77.27% with strong (+++), 21.21% with moderate (++) and 1.52% with weak intensity (+)." (PMID 30823889, 2019). "Altogether, this data indicates that the expression of SMC1A increases during colorectal tumorigenesis, from normal mucosa to carcinoma." (PMID 30823889, 2019). "Taken together, the results obtained in the present study demonstrate that the microRNA miR-9 negatively regulates SMC1A expression in GBM cells which reduces cancer cell growth and increases apoptosis." (PMID 28868238, 2017). "Recently, Wip1, an important signaling protein in cellular growth following DNA damage, has been identified as an upstream regulator of SMC1A, further suggesting an important role for this protein in cancer and chemotherapeutic response." (PMID 24699359, 2014). "A subsequent study expanded this initial proof-of-principle to include five additional genes, which are frequently mutated in cancer (CDC4, MRE11A, RNF20, SMC1A, and SMC3) that are also selectively killed following FEN1 inhibition." (PMID 24202319, 2013). "SMC1A has been identified as a proto-oncogene in the majority of cancers that may facilitate the growth and spread of cancer." (PMID 37537540, 2023). "Furthermore, we also found that SMC1A plays a positive correlation with the induction of cancer stem cells (CSCs)." (PMID 37096492, 2023). "We propose that a similar mechanism is at work in SMC1A-R586W cancers, and that this multi-hit model may be generalizable to other cohesin loss-of-function mutations in a variety of cancers." (PMID 33760811, 2021). "Also, genes STAG2 and U2AF1 were detected as drivers in AML and SMC1A in distinct cancers by the IntOGen tool." (PMID 26886259, 2016). "Recent studies have concluded that SMC1A is involved in the pathogenesis of cancer." (PMID 25884313, 2015). "In addition, SMC1A silencing induced apoptosis, as characterized by the prominent presence of sub-G1 apoptotic cancer cells." (PMID 23426528, 2013). "While cancer-associated mutations in genes encoding RAD21, SMC3, and STAG1 are always heterozygous, mutations in the X chromosome-located genes SMC1A and STAG2 can result in complete loss of function due to hemizygosity (males), or silencing of the wild type during X-inactivation (females)." (PMID 33284104, 2020). "In addition, since most of them are involved in cancer development their differential expression could explain the aggressiveness of SMC1A c.A2027G tumors." (PMID 30823889, 2019). "In support of this model, elevated expression of almost every cohesin subunit (RAD21, SMC1A, SMC3, STAG1, PDS5, WAPL) and cohesin regulator (NIPBL, MAU2) appears to be oncogenic and present in a wide range of cancer cells." (PMID 41370327, 2025). "To define the contribution of Mediator and Cohesin to the regulation of the cancer transcriptional program, we established the genome-wide occupancy of MED1 (Mediator), SMC1A (Cohesin) and the cohesin loader NIPBL." (PMID 27739523, 2016).
cancer (continued). "Transcription factors were ranked based on their percentage of overlap with MED1, SMC1A and NIPBL across the genome of each cancer cell." (PMID 27739523, 2016). "For instance, SMC1A, CDC20, SMAD3 and BUB1 are all example AbG-0.5 kb genes known to promote cell cycle progression and proliferation in various cancer cell types." (PMID 24086155, 2013). "SMC1A is a member of the SMC superfamily and a core component of the cohesin complex essential for sister chromatid cohesion and plays an essential role in cancer." (PMID 37212524, 2023). "Interestingly, inhibition of SMC1A in a model of DU145 and PC3 cells limited the clonogenic, EMT, and cancer stem-like cell (CSC) properties of cancer cells and rendered them more susceptible to RT." (PMID 34199763, 2021). "Moreover, we have identified an edge relating the genes with transmembrane protein function with those from the spliceosome (U2AF1, and USP9X) and the cohesin complex (SMC1A and STAG2) that have an important role in cancer." (PMID 26886259, 2016). "HUWE1 revealed exclusively monoallelic enrichment for all three marks, consistent with its silence on the Xi in all lines, whereas escapees SMC1A and DDX3X and several “cancer-specific” escapees displayed biallelic H3K4me3 and RNA Pol II, with monoallelic H3K27me3." (PMID 25653311, 2015). "It has been suggested that SMC1A participates in CRC tumorigenesis by promoting aneuploidy and we have previously shown that colorectal tissues acquired extra-copies of SMC1A during tumorigenesis and its expression is significantly more robust during cancer progression." (PMID 38365745, 2024). "In contrast, inactivation of the cohesin ring subunits SMC1A, SMC3, and RAD21 is not compatible with viability in both primary non-transformed human cells and human cancer cell lines." (PMID 30975996, 2019).
tumor (28 papers, 2013 to 2025). "Overexpression of the SMC1A has been shown to be associated with tumor progression and poor prognosis." (PMID 39851557, 2025). "As reported in CRC, the high expression of SMC1A promotes liver metastasis by recruiting the tumor-associated-fibroblastas (TAFs) to facilitate prophase tumor construction and tumorigenicity." (PMID 37537540, 2023). "A similar decrease in pluripotency was also observed in mouse ES cells deficient for Stag1/2, or with tumor-derived cohesin mutations in Stag2 or Smc1a." (PMID 34202641, 2021). "We observed that SMC1A levels were strongly associated with tumor-associated macrophages (TAM), M1, M2, neutrophils, Th2, Tregs, and monocytes." (PMID 34527684, 2021). "Notably, we found that tumor reduction and mouse survival induced by SMC1A silencing and bevacizumab are associated with high levels of abnormal mitotic figures and spontaneous micronuclei, which are markers of chromosome aneuploidy." (PMID 38365745, 2024). "In conclusion, these data suggested that high SMC1A levels may be associated with tumor immunosuppression." (PMID 37096492, 2023). "SMC1A holds sister chromatids during the cell division, reducing the proliferative activity in tumor cells." (PMID 40390497, 2025). "NUDT21 siRNA therapy works by promoting tumor apoptosis through the regulation of the 3′UTR plus tail of the SMC1A gene." (PMID 40390497, 2025). "Taken together, these data suggest that SMC1A silencing leads to a decrease in tumor volume and an increase in overall survival and these outcomes are improved by the combo treatment, SMC1A inhibition plus bevacizumab." (PMID 38365745, 2024). "Performing xenotransplant experiments in immunodeficient mice, we found that administration of SMC1A-specific shRNA reduces tumor growth and increases the overall survival." (PMID 38365745, 2024). "Next, we investigated the effects in vivo of SMC1A silencing on the development of tumor xenografts in immunodeficient mice." (PMID 38365745, 2024). "In this study, we found that SMC1A was upregulated in GC tumor tissues and cells, and high expression of SMC1A was associated with the poor overall survival." (PMID 37537540, 2023). "The tumour sizes and volume in SMC1A-overexpressing group were larger than those in the vector group." (PMID 37537540, 2023). "Similar to the results of TCGA and CPTAC databases, the protein expression levels of SMC1A were significantly higher in tumor tissues of CRC than in normal tissues." (PMID 37096492, 2023). "Among these nuclear proteins, we found an interesting candidate, SMC1A, that has a well-established function and mechanism and has a known tumor-promoting role in COAD30." (PMID 37932451, 2023). "The results showed that the expression of SMC1A and RNAss were positively correlated with COAD, which means that the higher the levels of SMC1A expression the stronger the tumor stemness." (PMID 37096492, 2023). "To understand the tumor cell-autonomous mechanism underlying the tumor-promoting function of SMIMP and SMC1A, we further investigated the two targets cyclin-dependent kinase inhibitor (CDKN)1A and CDKN2B that have an established role in cell proliferation." (PMID 37932451, 2023). "A similar pattern is observed at the tumor suppressor and Super-enhancer Domain gene Tet2, whose expression is decreased by 65% in SMC1A-R586W mESCs." (PMID 33760811, 2021). "We observed that LIG1, MRE11A, RAD9 and SMC1A levels were up-regulated in tumor cell lines when compared to normal PHK or to PHK expressing HPV genes." (PMID 30674977, 2019). "The SMC1A expression level was completely suppressed in tumor tissues by the infection with SMC1A shRNA." (PMID 25884313, 2015). "We found that SMC1A inhibition resulted in significantly impaired proliferation and colony formation as well as reduced invasiveness of tumor cells." (PMID 23426528, 2013).
tumor (continued). "High levels of phosphorylation on SMC1A were associated with advanced tumor grade and negative hormone receptor status (estrogen receptor, progesterone receptor, and HER2)." (PMID 39851557, 2025). "In addition, in an experimental model, overexpression of SMC1A reduced tumor latency and significantly increased tumor size." (PMID 38365745, 2024). "SMC1A may be a bidirectional target switch that simultaneously regulates the immune microenvironment and tumor stem cells." (PMID 37096492, 2023). "However, few reports have shown the effects of structural maintenance of chromosomes 1 (SMC1A) on the immune microenvironment and tumor stem cells." (PMID 37096492, 2023). "Meanwhile, a greater tumor weight was found in SMC1A-overexpressing group." (PMID 37537540, 2023). "To identify the common targets of SMIMP and SMC1A that are important for mediating their tumor-promoting function, we generated SMC1A chromatin IP (ChIP) followed by sequencing (ChIP–seq) data and performed an integrated analysis of RNA-seq, SMC1A ChIP–seq and TCGA data." (PMID 37932451, 2023). "SMC1A expression was evidently higner in tumor tissues compared with paracancerous tissues (Nomal)." (PMID 37537540, 2023). "We further validated the effects of SMC1A overexpression on tumor growth in vivo by subcutaneously inoculating AGS cells transfected with either blank vector or SMC1A overexpression vector into nude micein AGS cells on the growth of human GC xenograft formation in nude mice." (PMID 37537540, 2023). "However, it was rarely reported that SMC1A also acted as essential effects on tumor immune infiltration and CSCs in CRC." (PMID 37096492, 2023). "In conclusion, SMC1A may be a bidirectional target switch that simultaneously regulates the immune microenvironment and tumor stem cells." (PMID 37096492, 2023). "However, few reports have shown the effects of SMC1A on the immune microenvironment and tumor stem cells." (PMID 37096492, 2023). "Conversely, SMC1A-R586W may represent a second hit that creates conditions permissive to oncogenesis, where benign neoplasias can adopt more aggressive characteristics." (PMID 33760811, 2021). "Evidence from previous studies suggests that the chromatid cohesion defects may underlie chromosome instability and tumour development, emphasizing the role of SMC3 and SMC1A as candidate drivers." (PMID 33319839, 2020). "The SMC1A 1^4 FS immunization also significantly retarded the 4T1 tumor growth in BALB/c mice." (PMID 31578439, 2019). "Therefore, we focused on the 125 downstream targets, the expression of which was co-repressed by SMIMP and SMC1A and may play a tumor-suppressive role." (PMID 37932451, 2023). "Additionally, overexpressing the wild type, but not the M4 deletion mutant SMIMP, mitigated the loss-of-function phenotype of SMC1A on cell growth and colony formation, suggesting a role of SMIMP–SMC1A interaction in modulating the tumor-promoting properties of SMC1A." (PMID 37932451, 2023). "Moreover, SMC1A expression plays a crucial role in function of various T cell populations while it may be a predictive marker of immune checkpoint inhibitor therapy, in a tumor setup." (PMID 39871364, 2025). "We found that PIK3R3 upregulated the expression of CDKN1C, downregulated the expression of SMC1A, and activated Akt signaling, thereby promoting HCC cell proliferation and tumor growth." (PMID 37212524, 2023). "Consistent with the reported tumor-promoting role of SMC1A30 and elevated expression of SMC1A in COAD tumor tissues compared with normal colon tissues, we confirmed that siRNA-mediated silencing of SMC1A suppressed CRC cell growth and colony formation." (PMID 37932451, 2023). "To validate the involvement of SMC1A in the tumor stemness of COAD, we measured the mRNA levels of SMC1A with tumor stemness scores from TCGA database." (PMID 37096492, 2023).
tumor (continued). "In conclusion, knockdown PIK3R3 inhibits the tumor growth of HCC by upregulating the expression of CDKN1C and downregulating the expression of SMC1A by deactivating the Akt pathway and inhibiting cell proliferation and colony formation." (PMID 37212524, 2023). "Proteomic profiling further revealed its impact on multiple oncogenic and tumor-suppressive proteins, with notable upregulation of SERPINB2, KIT, and NOTCH1, alongside downregulation of COX2, DNMT1, MAPK1, AKT1, MKI67, EP300, and SMC1A." (PMID 41321870, 2025). "Collectively, our data suggest that in the absence of SMC1A, cell proliferation and tumor development were efficiently suppressed." (PMID 38365745, 2024). "In addition, consistent with previous research results, we also found that SMC1A, SMC1B, SMC2, SMC3, SMC4, and SMC6 were overexpressed at the mRNA level in HCC when compared with non-tumor cells." (PMID 34527684, 2021). "In the absence of SMC1A, cell proliferation, cell cycle progression and tumor development were effectively suppressed." (PMID 25884313, 2015).
) malformation syndrome (2 papers, 2018 to 2022). "The best characterized cohesinopathy is CdLS, an autosomal dominant (NIPBL, SMC3, and RAD21) or X-linked (SMC1A and HDAC8) malformation syndrome." (PMID 36467423, 2022).
gynecological diseases (1 paper, 2021). "However, there was no relative study about SMC1A expression in the human endometrium or any gynecological diseases, which limited the function of SMC1A in this disease." (PMID 33653363, 2021).
SMC1A also shares sentences with these, for which no sentence is quoted: infection (4 papers); Warsaw breakage syndrome (4); chronic atrial and intestinal dysrhythmia (3); genetic disorder (2); glioblastoma (2); Kabuki syndrome (2); neurodevelopmental disorder (2); neurological disorders (2); Angelman syndrome (1); ataxia-telangiectasia-like disorder (1); Athetosis (1); Barth syndrome (1); blood cancers (1); Bloom syndrome (1); breast adenocarcinoma (1); cervix cancer (1); chronic myelogenous leukemia (1); Coffin-Lowry syndrome (1); colon adenocarcinoma (1); cystic fibrosis (1); Danon disease (1); dedifferentiated liposarcoma (1); developmental disabilities (1); diaphragmatic hernia (1); Dystonia (1); episodic ataxia (1); Ewing sarcoma (1); Fanconi anemia (1); focal dystonia (1); heart diseases (1).
A further 25 diseases each share a sentence with SMC1A in 1 paper.